MYC (MYC proto-oncogene, bHLH transcription factor)
Diseases named in the same sentence as MYC in open-access papers (continued):
Sharing a sentence is not in itself a finding about the gene and the disease.
tumor (continued). "Interestingly, in tumor cells with high MYC expression, MIZ-1 was found to occupy many more sites in a MYC-dependent manner, indicating a mechanistic difference between the physiological and oncogenic properties of MYC." (PMID 28505071, 2017). "Finally, to determine the impact of MYC activation on prognosis, we classified TCGA KIRP tumours as MYC activated (n=23, defined as tumours with a Z score of the PID_MYC_ACTIV_PATHWAY greater than 1.0 s.d. above the mean) or not MYC-activated (n=153)." (PMID 28593993, 2017). "In contrast, the oncogenes MYC and MYB, the expression of which is driven by the WNT pathway in CRC, remained elevated in quiescent and proliferating LGR5+ tumor cell populations." (PMID 28468934, 2017). "In the intrinsic pathway of inflammation-induced cancer, MYC and RAS family oncogenes remodel the tumour microenvironment by activating transcriptional factors through recruitment of leucocytes, lymphocytes, chemokines, cytokines expression, and angiogenic switch induction." (PMID 28275390, 2017). "KEGG pathway enrichment analysis showed that CCNE2, MYC, CREB3L4, and NKD2 are involved in many tumor-related pathways, suggesting that these genes may play an essential role in cancer development." (PMID 28056099, 2017). "While deletion of MYC in the myeloid compartment does not result in alterations in terms of cell number or distribution of macrophages and their progenitors in steady-state, deletion of MYC in macrophages attenuates the pro-tumor function of TAM and suppresses tumor growth." (PMID 28245597, 2017). "Taken together, we propose a working model in which MYC, in addition to its role as a site-specific transcription factor, controls DNA methylation in a global manner through overexpression of DNMT1 and DNMT3B during tumor maintenance." (PMID 29100357, 2017). "Given that subversion of apoptosis is an essential step in MYC-driven lymphomagenesis, it has long been suggested that EBV may provide protection against intrinsic apoptosis in the established tumour." (PMID 29137176, 2017). "With respect to targeting of MYC, downregulation of MYC mRNA expression can be achieved by bromodomain and extra-terminal motif (BET) inhibitors in certain tumor types, while targeting the PI3K/mTOR pathway is known to affect both MYC turnover and mRNA translation." (PMID 28665315, 2017). "In the present study, we assessed the relative expression level of MYC in tumor tissues regardless of its genomic amplification." (PMID 28480695, 2017). "In MYC-overexpressing TNBC patient-derived xenografts, researchers have used metabolomics analysis to identify a lipid metabolism gene signature and they have shown that pharmacological inhibition of fatty acid oxidation (FAO) can decrease tumor growth." (PMID 28696357, 2017). "In addition, MYC transcriptionally represses microRNAs miR29a and miR29c, which results in enhanced expression of MCT1 on tumor cells." (PMID 28362357, 2017). "Here these dormant tumor cells later give rise to tumors that are independent of MYC or have become refractory to MYC inhibition." (PMID 28333115, 2017). "This is exemplified by studies showing that tumor initiation likely occurs before the sympathoadrenal stage, as MYC expression in differentiated sympathoadrenal cells did not induce tumor formation in previous models." (PMID 29238067, 2017). "MB-LU-181 xenografts replicated the phenotype of the primary tumour, including histology, expression and amplification of MYC and presence or absence of distinct tumour markers." (PMID 28417956, 2017). "Perhaps the most obvious contradiction is that the degree and duration of oncogenic RAS activation would have profound effects on MYC protein accumulation and thus enhance rather than decrease tumor sensitivity to chemotherapy or radiotherapy." (PMID 28152508, 2017).
tumor (continued). "So whether a patient's tumor is driven by STAT3, MYC, Notch or a combination, they could still be treated with a CCT inhibitor since the chaperonin is essential for these proteins to reach functional status." (PMID 29299146, 2017). "However, MYC inactivation in tumors due to enforced CD47 or PD-L1 expression leads to suppressed immune responses and continued tumor growth." (PMID 28757546, 2017). "Cell death amount in the stromal compartment and MYC protein level in the tumour were highly correlated regardless of tumour type and stage." (PMID 28974715, 2017). "Additionally, in studies using the BET inhibitor JQ1 have shown that the ability to modulate c-MYC in models of DLBCL correlated to decreased cell viability and tumor growth suppression." (PMID 28178345, 2017). "By creating mice models carrying one extra copy of either MYC alone or the region co amplified with MYC, including the PVT1 gene, Tseng and colleagues demonstrated that in these experimental settings only the combination of both MYC and PVT1 is able to drive neoplasia." (PMID 28704924, 2017). "It was demonstrated that JQ1 could block tumor growth and a recurring feature of the consequences of JQ1 / I-BET151 treatment was inhibition of MYC, N-MYC or FOSL expression, respectively in these tumors." (PMID 26623725, 2016). "Preliminary results indicate that DNMT3B and MYC are able to interact in RD cells (Megiorni & Marampon, unpublished data), suggesting a possible molecular mechanism for site-specific DNA methylation/repression of target genes in ERMS tumours." (PMID 27764816, 2016). "Since the MYC pathway promotes apoptosis via the intrinsic BCL2- dependent pathway, it is reasonable that the regulation of this survival pathway is both necessary and sufficient for the GCB tumor survival." (PMID 27102442, 2016). "In addition, they showed that this dietary pattern can down-regulate tumor suppressor miRNA-143 and miRNA-145 through EGFR signaling, which further up-regulated their target oncogenes, MYC and KRAS, resulting in increased tumorigenesis." (PMID 27681738, 2016). "In these tumours, BPTF expression levels also correlated positively with c-MYC signatures." (PMID 26729287, 2016). "Together, the results imply that the MYC transcription factor regulates distinct sets of genes in normal and tumor cells according to how much MYC is present." (PMID 27460974, 2016). "Furthermore, following the fact that rDNA transcription is greatly influenced by the RAS, MYC, and NPM oncogenes, DHX33 upregulation was shown to be required for enhanced transcription during RAS activation and for RAS-initiated tumor progression." (PMID 27198694, 2016). "Downregulation of MYC was also confirmed on transcript and protein level in DEV cells after coculture and in 12/16 primary LP-DLBCL with > 90% MYC-negative tumor cells." (PMID 27708232, 2016). "Cancer cell proliferation and capacity for transformation were impaired in the CD133 stable knockdown cell lines, which were accompanied by the suppression of stemness genes including NANOG, OCT4, SOX2, and c-MYC, suggesting that CD133 expression is required for tumor tissue growth and survival." (PMID 26539911, 2015). "Unexpectedly, one Notch target gene that is strongly correlated with response to Notch inhibition in cortical T-ALL, MYC, was not under the control of Notch in this tumor." (PMID 27148573, 2015). "Intra-tumor heterogeneity was found in the primary tumors of 9 of 19 (47.3%) cancers with HER2, 8 of 17 (47.0%) cancers with CCND1, 5 of 7 (71.4%) cancers with EGFR, and 23 of 27 (85.2%) cancers with MYC amplification." (PMID 25649416, 2015). "For the MYC and LKB1, several lines of evidence show they are in opposite action in tumor." (PMID 26083494, 2015).
tumor (continued). "We selected MYC and CCND1 mRNA levels as these two genes are considered extremely relevant in the G0 – G1 cell cycle transition and S phase entry, being key factors for tumor development, growth and progression." (PMID 25671297, 2015). "We observed that the expression levels of the phosphorylated active form of MTOR (pMTOR) and YY1 were significantly elevated at as early as one month of age and persistently activated throughout the study period, while MYC and SLC2A1 expression was found upregulated only upon tumor formation." (PMID 25909713, 2015). "miR-34 targets prototypical oncogenes such as MET, MYC, and BCL2, thus acting as tumor suppressor." (PMID 26583081, 2015). "It has been plausibly suggested that gains of 8q target MYC in OS, but chromosome 8 gains in our set of tumours involved very long segments without evidence of targeting any gene specifically." (PMID 26632267, 2015). "Finally, downregulation of cyclin D1, c-MYC, survivin, c-Met, EGFR, Src, FAK, and α-tubulin expression was observed in 786-O tumor xenografts treated with ART." (PMID 26426994, 2015). "Although WNT tumors express high levels of AURKB mRNA we did not observe a correlation to MYC mRNA expression in this small subset of tumor samples (R=0.42, P=0.3, N=8)." (PMID 25739120, 2015). "Lack of response of MYC to Notch inhibition can be explained by the inactivate state of the Notch-dependent MYC long-range enhancer (NDME) in this tumor, which appears instead to rely on a BRD4-dependent long-range enhancer (BDME) defined previously in AML." (PMID 27148573, 2015). "Formalin-fixed paraffin-embedded tumor tissues were collected from 338 M0 patients (>4.0 years at diagnosis) for pathology review and assessment of the WNT subgroup (MBWNT) and genomic copy-number defects (chromosome 17, MYC/MYCN, 9q22 (PTCH1) and DNA ploidy)." (PMID 26420814, 2015). "Indeed, TRPS1 and Cath-D co-repress transcription of secreted protein rich in cysteine gene (SPARC), a tumor suppressor in MDA-MB-231 ER− BCC and promote c-MYC and TGFB3 expression." (PMID 26183398, 2015). "These miRNAs are tumor suppressors by targeting oncogenes including Ras, HMGA2 and MYC." (PMID 26244871, 2015). "BIN1 has tumor-suppressor activity by interacting with and activating MYC-mediated apoptosis, except when exon 12A is included by SRSF1-mediated alternative splicing, because the resulting antiapoptotic BIN1+12A isoform is unable to interact with MYC." (PMID 26273603, 2015). "DNMTs and N-MYC protein expression was analyzed in 10 MYC translocation-positive and 10 MYC translocation-negative BL tumor samples by immunohistochemistry." (PMID 26453442, 2015). "In patients, a negative relationship between MYC expression and progression-free and overall survival has been described, suggesting an important role for MYC in the regulation of tumor mass." (PMID 26087190, 2015). "Thus CIP2A controls oncogenic transcription in tumor cells and the “oncogenic nexus” of CIP2A protein in human malignancies is executed through the stabilization of MYC protein involving PP2A." (PMID 25015035, 2014). "Furthermore, we found that 4EGI-1 selectively inhibits translation of mRNAs encoding proteins that are enhanced in CSC maintenance, proliferation and metastasis, such as NANOG, OCT4, c-MYC, cyclin D1, CXCR4, VEGF and c-MYB, in breast CSC tumor cells." (PMID 25115391, 2014). "miR-34a has tumor-suppressive properties in DLBCL, and its expression is directly regulated by MYC." (PMID 24887414, 2014). "Therefore, in tumor cells, where MYC levels are generally elevated, HIF-1α will only inhibit MYC activity during short periods of severe hypoxia, whereas, at other times, the high MYC levels can drive cellular proliferation." (PMID 25085992, 2014).
tumor (continued). "Furthermore, silencing CIP2A expression influenced MYC protein expression and further suppressed NPC cell proliferation and tumor growth." (PMID 24884612, 2014). "In addition, we found the similar SNV frequency in a set of oncogenes and tumor suppressors, such as CBL and MYC, between primary tumors and metastases." (PMID 24405831, 2014). "Despite these promising demonstrations, JQ1 does not inhibit MYC expression to a similar extent in all tumor cells." (PMID 24466310, 2014). "However, combination treatment of MYC-CaP/CR tumors with AUY922 and docetaxel significantly reduced tumor growth compared to each single treatment arm." (PMID 25072314, 2014). "Moreover, MYC is upregulated during hypoxia via a HIF-dependent mechanism and plays a major role in regulating physiological and tumor angiogenesis and inflammation." (PMID 25374893, 2013). "We have shown that CYCLON deregulation is predominant, albeit not exclusive to, ‘high MYC’ DLBCL tumours, of both the GCB and ABC subtypes." (PMID 23828858, 2013). "It remains to be elucidated which cells of the immune system contribute to anti-cMYC-specific anti-tumor activity and whether c-MYC NHP-B specific CD4+ T-cells are required for long term tumor rejection in this model system." (PMID 24130880, 2013). "In the present study, we observed expression changes and epigenetic modulations of several key tumor-related genes, including tumor suppressor genes, p21WAF1 (p21) and p16INK4a (p16), and tumor promoting genes, BMI1 and c-MYC, during early breast tumorigenesis in vitro and in vivo." (PMID 23342141, 2013). "Furthermore, at the smaller-genomic scale level, ALK fusion-positive tumours were less amplified at the loci containing EGFR family genes, 7p11.2 (EGFR), 17q12 (ERBB2) and other loci, 1p34.3 (MYCL), 7p21.1, 8q24.21 (MYC), 16p13.3 and 17q25.1." (PMID 23289484, 2013). "The function of FBXO28 in regulation of MYC activity is also supported by the findings that depletion or functional inactivation of FBXO28 attenuates MYC-induced transformation in vitro and MYC-driven tumour growth in vivo." (PMID 23776131, 2013). "Furthermore, GE treatment increased expression of two crucial tumor suppressor genes, p21WAF1 (p21) and p16INK4a (p16), although it decreased expression of two tumor promoting genes, BMI1 and c-MYC." (PMID 23342141, 2013). "Recent studies have demonstrated that let-7 might act as a tumor suppressor and that reduced let-7 level results in let-7-responsive gene (cyclinD, RAS, MYC, etc.)overexpression in tumors." (PMID 22761738, 2012). "Taken together, a higher tumor grade was accompanied by a correlating, increasing expression of c-MYC and SIRT1 irrespective of the histologic subtype and side of localization." (PMID 23045412, 2012). "Importantly, coexpression of MYC together with BCL-XL/BCL-2 resulted in strongly accelerated kinetics and favored tumor development towards aggressive AML." (PMID 22393362, 2012). "Moreover, the pleiotropic miR-24, in addition to its regulation of ARF, has been shown to repress expression of MYC and E2F2, which are important in driving proliferation and imperative to tumor growth." (PMID 22336108, 2012). "In this subgroup, patients without MYC amplification in their tumor do equally poor as those carrying this alteration." (PMID 22358457, 2012). "First, it should be noted that all previous studies on the relation between MYC and FLIPL has been performed in cell cultures in vitro, and may be less relevant for tumor development in vivo." (PMID 22393362, 2012). "Tumor cell lines could be established from all moribund Mock/MYC, MYC/BCL-XL, MYC/BCL-2 and MYC/FLIPL recipient mice." (PMID 22393362, 2012).
tumor (continued). "Because MYC is a central regulator of the cell cycle and aberrant MYC expression plays a central role in oncogenesis, Kress and colleagues investigated the state of MK5 expression in tumour cells with increased MYC levels." (PMID 22800433, 2012). "No change in MYC expression was observed in the tumor biopsy of this animal after 20 days of Canova treatment." (PMID 21811552, 2011). "Alternatively, the observed correlation of MYC and NDRG2 mRNA expression in breast tissue may result from a shared regulatory mechanism of these genes in the normal and tumor samples tested." (PMID 21226903, 2011). "We have shown that RNA isolated from FFPE tumor tissue samples, amplified following the MessageAmp Premier protocol, and hybridized to Affymetrix arrays can be used to generate consistent and reliable genomic profiles reflecting RAS and MYC pathway activity." (PMID 21745407, 2011). "Using the human B-cell derived p493-6 and the human NB-derived Tet21 N cell lines with conditional expression of c-MYC and MYCN respectively, we show that a limited number of agents, acting through distinct mechanisms, are more effective in MYC overexpressing tumor cells." (PMID 22132187, 2011). "All these effects of MYC may contribute to tumour cell metastasis driven by CIP2A, and further study is required to elucidate the role of MYC in CIP2A-mediated RCC metastasis." (PMID 22075943, 2011). "One possibility is that MYC is expressed at a high level across all tumours irrespective of the copy number status and hence is not different between groups of tumours that show a gain and those that do not." (PMID 20386695, 2010). "Whereas non-SP cells formed fewer and slower-growing tumours, SP cells over-expressed many genes associated with cancer stem cell and drug resistance: ABCG2, FGF1, IGF1, MYC, SOX1/2, WNT1, as well as genes involved in angiogenesis, Notch and Hedgehog pathways." (PMID 20424609, 2010). "The results demonstrated that tumor growth in Pim1-expressing PC3 cells was accelerated compared to control cells, and this could be partly due to c-MYC protein induction." (PMID 20515470, 2010). "Inducible expression or function of transgenic c-MYC demonstrated cooperation with mutant K-Ras in tumor progression to various degrees but neither model gave rise to metastasis." (PMID 19551151, 2009). "Interestingly, this was accompanied by an overexpression of c-MYC antagonists MAD1 and MXI1 in many tumours." (PMID 18493233, 2008). "Taken together these results suggest continuously activated CM mice develop lung tumors that become independent of MYC for tumor maintenance." (PMID 18461184, 2008). "If BCR signalling is truly crucial for the formation of tumours in EμMYC/BCRHEL, EμMYC/BCRHEL/sHEL, and MMTV-rtTA/TRE-MYC/BCRHEL/sHEL mice, then these lymphomas should be sensitive to immunosuppressive drugs that block the BCR signalling pathway at particular points." (PMID 18578571, 2008). "Mice transgenic for MMTV-rtTA/TRE-MYC/BCRHEL did not develop tumours if they were treated with doxycycline to repress MYC expression." (PMID 18578571, 2008). "To directly test this hypothesis, we simulated double targeted treatment of MYC and K-rasG12D using dual conditional CMR tumor laden mice by inactivating both oncogenes and then comparing similarly to the single CM and CR mice." (PMID 18461184, 2008).